BCL2 (BCL2 apoptosis regulator)
Diseases named in the same sentence as BCL2 in open-access papers (continued):
Sharing a sentence is not in itself a finding about the gene and the disease.
cancer (continued). "The combinatorial effect of withaferin A and sulforaphane was also observed in MDA-MB-231 and MCF-7 breast cancer cells, with a dramatic reduction of the expression of the antiapoptotic protein Bcl-2 and an increase in the pro-apoptotic Bax level, thus promoting cancer cell death." (PMID 37259311, 2023). "The unbalanced expression of BCL2 is often related to various diseases including cancer." (PMID 37047536, 2023). "In addition, the dysregulation of Bcl‐2 is a key factor in distinguishing normal cells from cancer cells." (PMID 36852470, 2023). "On one hand, the combination of BCL-2 and PD-1/PD-1L inhibitors promotes cancer cell death; on the other hand, it may result in the shortened survival of T lymphocytes." (PMID 36902139, 2023). "Bcl-2 is an oncogene that inhibits apoptosis and cancer progression." (PMID 36937441, 2023). "Inhibition of SAAL1 expression could inhibit cancer cell proliferation, which may be related to the decreased expression of cyclin D1 and Bcl-2 proteins." (PMID 36973678, 2023). "Bcl2 belongs to the anti-apoptotic Bcl2 family and is required for cancer cells to survive." (PMID 36959600, 2023). "Therefore, the inhibition of BCL2 has been considered to be a viable approach to eradicating residual cancer cells." (PMID 37679323, 2023). "Bcl-2 expression or function dysregulation contributes to cancer development and progression." (PMID 37834104, 2023). "Recently, it has been reported that cancer might induce muscle atrophy by targeting Bcl-2-mediated apoptosis and overexpression of Bcl-2 successfully reversed atrophy of C2C12 myoblasts." (PMID 38180061, 2023). "Studies with some cancer cells also demonstrate that the ability of ouabain to initiate apoptosis correlates with reduced expression of the anti-apoptotic proteins Mcl-1, Bcl-XL, and Bcl-2, or increased expression of the pro-apoptotic proteins Bid and Bax." (PMID 36830836, 2023). "The Bcl-2 protein inhibition is a promising therapeutic target for developing new anticancer drugs because it is a key regulator of the intrinsic apoptosis pathway involved in various cancers." (PMID 36838574, 2023). "In addition, immunoblotting and TUNEL stain in DOX-treated cancer cells revealed upregulation of mitochondrial pro-apoptotic protein Bax, higher ratio of Bax/Bcl-2, and a 10-fold increase in cell apoptosis." (PMID 36632235, 2023). "It targets cancer cells in vitro (against HepG2 cells) 14 times more specific than cisplatin via downregulating the expression c-Myc, hTERT, and Bcl-2 with 73%, 52%, and 90%, respectively, and its in vivo inhibition of tumor growth was as good as that of cisplatin." (PMID 36456886, 2023). "Based on the fact that pro‐survival BCL‐2 proteins are frequently linked with cancer progression and chemotherapy resistance, a number of highly specific BH3‐mimetic compounds have been developed, including pan‐BCL‐2‐targeting ABT‐737/ABT‐263, MCL‐1‐targeting S63845, and BCL‐2‐targeting ABT‐199." (PMID 37846472, 2023). "A drug that can increase Bax expression and decrease Bcl-2 expression can prevent cancer growth." (PMID 36937441, 2023). "The genetic overexpression of Bcl-2 and Bcl-xL is found in many human cancers." (PMID 37686541, 2023). "Vitexin, an extract of the Chinese herb known as Crataegus pinnatifida, is a flavonoid that has been demonstrated to kill cancer cells by decreasing the Bcl-2/Bax ratio, mitochondrial cytochrome c release, and caspase-3 cleavage in human non-small cell lung cancer A549 cells." (PMID 37110140, 2023). "However, this balance is disrupted by the increase in the BCL-2 level in cancer cells, and subsequently, the inhibition of apoptosis is the main result of this disturbance." (PMID 36976217, 2023). "However, cancer cells are able to eradicate mitochondrial caspase-independent apoptosis machinery by up-regulating Bcl-2 anti-apoptotic proteins." (PMID 37024466, 2023).
cancer (continued). "In particular, CDK9 emerged as a druggable target for the development of cancer therapeutics, due to its crucial role in the transcriptional regulation of both short-lived anti-apoptotic proteins and oncogenes, such as BCL2/6 and MYC, critical for the survival of transformed cells." (PMID 37457123, 2023). "Also, in BM cancer cells, MSCs upregulated Bcl-2 and boosted survival rates in the context of acute myeloid leukemia." (PMID 37686315, 2023). "Increased BCL-2 expression might enhance anti-apoptotic activities, thus preventing the complete digestion of the entrapped cancer cells inside macrophages." (PMID 37848444, 2023). "In combination with BCLxL/BCL2 inhibitors, splicing modulators can enhance cytotoxicity through broader inhibition of the BCL2 family genes that act cooperatively to promote anti-apoptosis/pro-survival in cancer cells." (PMID 37562845, 2023). "Venetoclax (ABT-199, BCL2 inhibitor), the best known and trialled BH-3 mimetic, is a small-molecule proapoptotic drug with significant clinical activity, that is considered practice-changing for several adult cancers." (PMID 37189994, 2023). "Moreover, the overexpression of Bcl-2 potentiates senescence cancer cells, such as in K562 leukemia cells." (PMID 37047342, 2023). "Therefore, the Bax/Bcl-2 ratio is a critical factor for the determination of anti-apoptosis activities of anti-cancer agents in vitro and in vivo studies." (PMID 36984763, 2023). "Altogether, these results suggest that 5α-reductase inhibition may decrease cancer cell progression and migration via p21, Bcl-2, MMP2, MMP9, NF-κB, and GSK3β signaling pathways." (PMID 36800968, 2023). "Besides, it elevated the oxidative stress, the expression of key apoptotic genes and suppressed the expression of key oncogenes (NF-κB, BCL2 and cyclin D); implying its promising efficacy in cancer treatment as adjuvant drug." (PMID 38008815, 2023). "In cancer therapy, evidence shows that high levels of Bax:Bcl-2 ratio may result not only in decreased resistance to apoptosis but also in a better prognosis and a lower metastasis." (PMID 37108599, 2023). "Moreover, it exerts a regulatory effect on apoptosis within cancer cells through the modulation of the expression and activity of key apoptotic proteins such as BCL-2, BAX, and cleaved caspase." (PMID 38003971, 2023). "Moreover, Mcl-1 dependent cancers are resistant to pan Bcl-2/Bcl-xL inhibitors (ABT-737), and venetoclax." (PMID 36986514, 2023). "Increased expression of the anti-apoptotic BCL-2 gene was observed mainly in non-cancer cells." (PMID 37534254, 2023). "Additionally, the significant downregulation of the Bcl2 proteins was remarkable in magnifying the beneficial role of Pd (II) treatment through their activity to direct cancer cells to apoptotic mechanisms." (PMID 38139837, 2023). "Their therapeutic actions involve decreasing cancer cell viability and altering their morphology and levels of Bcl2 proteins, inflammatory markers, oxidative stress parameters and NF‐kappa whilst increasing Bax/Bcl2 ratio and levels of apoptosis." (PMID 37697969, 2023). "Failures of BCL-2 inhibition may rely on the survival dependence of cancer cells on numerous other anti-apoptotic proteins." (PMID 37108344, 2023). "In addition, elevated levels of anti-apoptotic BCL-2 proteins are also an effective strategy used by cancer cells to evade programmed cell death." (PMID 36369364, 2023). "A key feature of human cancers is intrinsic or acquired resistance to apoptosis, including upregulation of anti-apoptotic proteins (e.g., Bcl-2, Bcl-xL, IAPs) and pro-survival signaling pathways (e.g., PI3K/Akt, NF-kB) and/or downregulation of pro-apoptotic proteins (e.g., Bax, Bad, Bim)." (PMID 36677751, 2023).
cancer (continued). "In fact, it was reported that the overexpression of Bcl-2 confers chemoresistance to cancer cells." (PMID 37760033, 2023). "Therefore, it is crucial to realize that Bcl2 and Bcl-xL suppression causes advantageous apoptotic effects, which subsequently reduce CRC cancer growth." (PMID 37894369, 2023). "Therefore, we can conclude that the antitumor activity of the shikonin exerted against CAKI-2 and A-498 human cancer cells is mediated through the downregulation of antiapoptotic proteins, including Bcl-2." (PMID 37764501, 2023). "Bax, Bcl-2 and their ratios are considered prognostic markers of various cancers." (PMID 37404473, 2023). "The observed response of cancer cells to the combinational treatment with BCL-2 and MAPK inhibitors may be related to the phenomenon of cancer cell dependence on a specific oncogene to sustain growth and survival." (PMID 37108344, 2023). "Caspase-independent cell death, triggered by the down-regulation of anti-apoptotic proteins such as Bcl-2, might be a potential candidate for such anti-cancer alternative therapeutic strategies." (PMID 37024466, 2023). "A direct example of this is miR-139-5p’s ability to silence the cancer-promoting gene BCL-2." (PMID 37474869, 2023). "This review elucidates the crucial mutations of drug resistance and sheds light on the genetic or pharmacologic factors that hold promise for enhancing drug sensitivity, providing insights into further translational investigations of BCL-2 inhibitors in cancer treatment." (PMID 37894324, 2023). "Therefore, one of the pathways associated with apoptosis factors attended to be targeted for cancer therapy is the anti-apoptotic B-cell lymphoma-2 (Bcl-2) family of proteins, including Bcl-w and Bcl-xL Bfl1/A-1, Bcl-2, Mcl-1, and Bcl-B." (PMID 36820406, 2023). "Note should also be made of the pan-Bcl2 inhibitor R-(-)-gossypol (AT-101), an orally bioavailable polyphenol derived from the cotton plant, which has been investigated in several cancers and is presently under study for RRMM in combination with lenalidomide and dexamethasone (NCT02697344)." (PMID 36768967, 2023). "Thus, in the cancer context, it is common to observe an increase in the expression of anti-apoptotic family members, like BCL2, which happens to be one of the main contributors to B-cell lymphomagenesis." (PMID 37457123, 2023). "Bcl-2 over-activation results in the abnormal proliferation of cancer cells." (PMID 37021044, 2023). "Additionally, CHE NPs induced apoptosis in cancer cells by regulating the Bax and Bcl-2 antagonist of cell death (BAD) signaling." (PMID 37237914, 2023). "Our results indicated that cancer progression was potentiated by testosterone treatment and attenuated by 5α-reductase inhibition, leading to alterations in expression of cancer protein markers, including Bcl-2, MMP2, and MMP9." (PMID 36800968, 2023). "Therefore, the BH4 domain became a unique therapeutic target for recent efforts developing anti-cancer therapy through the alteration of Bcl-2 from a survival promoter to a death inducer." (PMID 37237269, 2023). "Venetoclax, a Bcl-2 inhibitor, reduced the increased tumorsphere size more efficiently in Nf2-KO S1 and NF2-KO SNU-668 cells than in control cells, indicating that Bcl-2 mediates the increased cancer stemness induced by NF2 deficiency." (PMID 37730636, 2023).
cancer (continued). "Moreover, it has been demonstrated that OXPHOS suppression in AML-engrafted mice can elevate cancer cell sensitivity to anti-BCL2 drug Venetoclax and Cytarabine." (PMID 37441073, 2023). "Indeed, to cope with oncogenic stress, cancer cells often rely on the upregulation of anti-apoptotic Bcl-2 proteins." (PMID 37391438, 2023). "Bcl-2 is known to exert an ant-apoptotic effect, supporting drug resistance in cancer cells." (PMID 36030493, 2023). "In particular, Bcl-2 concentrations are found to be upregulated in almost all cancers." (PMID 37893079, 2023). "In addition, paxillin can directly interact with the pro-survival proto-oncogene Bcl-2 to promote cancer cell survival." (PMID 37175948, 2023). "This massive down-regulation of the anti-apoptotic Bcl-2 by the DF test compounds, along with improved apoptotic rates in these samples, could explain the therapeutic value of these compounds for cancer therapy." (PMID 37736508, 2023). "BCL-2 is a key protein regulator of apoptosis and is overexpressed in many cancer types." (PMID 37193964, 2023). "Finally, it was found that HECP2k 10X@Dox/siRNA complexes caused synergistically enhanced anti-cancer effects of Dox and Bcl-2 siRNA in cancer cells via induction of apoptosis." (PMID 36840030, 2023). "However, venetoclax selectively binds to Bcl-2 and has limited efficacy against cancer cells that depends on other anti-apoptotic proteins for survival such as Mcl-1." (PMID 36658493, 2023). "Moreover, the stimulation of proapoptotic molecules such as caspase 3 and the inhibition of antiapoptotic molecules such as Bcl-2 are common therapeutically strategies to induce cancer cell death." (PMID 37361049, 2023). "Therefore, cancer cells that are highly dependent on pro-survival proteins such as Bcl-2 and/or Mcl-1 are less likely to respond to TRAIL-induced apoptosis." (PMID 36195672, 2023). "Similarly, the enforced expression of miR-34a (transfection of pre-miR-34a) was observed to target anti-apoptotic protein Bcl-2, c-Myc, Cyclin D1, E2F3 and Notch signaling pathway, causing the suppression of cancer cell proliferation, metastasis and invasion." (PMID 38139352, 2023). "Overexpression of the Bcl-2 protein is inherent in various cancers, including HNCs." (PMID 37371038, 2023). "One of the crucial genes to be silenced to prevent cancer development is the Bcl-2 gene." (PMID 37038689, 2023). "Moreover, Bcl2 and Sp1, which are miR-200b targets, were increased in cancer-derived endothelial cells when compared with healthy ECs that are characterized by very low miR-200b expression." (PMID 37261072, 2023). "Instead, the inhibition of the anti-apoptotic BCL2 proteins may represent an Achilles heel of chemoresistant cancer, and hence the application of BH3-mimetics in chemoresistant disease appears to be highly promising." (PMID 37723317, 2023). "The upregulation of Bcl-2 gene expression levels can promote the survival of the cancer cells, therefore the inhibition of the anti-apoptotic/pro-survival members of the Bcl-2 family of proteins is an attractive approach for combating cancer." (PMID 37845669, 2023). "The antiapoptotic activity of Bcl-2 confers resistance to chemotherapy in patients with cancer." (PMID 37064948, 2023). "This correlation between chemoresistance and miR-125b-5p expression level may be explained by its direct targeting of BCL2 mRNA, thereby increasing the sensitivity of cancer cells to cisplatin treatment." (PMID 37569592, 2023). "Furthermore, the relative gene expression of Bcl-2 was significantly downregulated in OVCAR-3 cancer cells treated with CMB for 24 h or 48 h to 0.70 and 0.33, respectively, compared to untreated control cells." (PMID 36770806, 2023). "Although inhibitors of Bcl-2 and Bcl-xL are effective in treating hematopoietic malignancies, efficacy is limited in primary solid cancers including GC partly because of a complex microenvironment that promotes cancer cell survival and resistance to treatment." (PMID 37730636, 2023).
cancer (continued). "Meanwhile, like other Bcl-2 anti-apoptotic members, high frequency of Mcl-1 gene amplification has been observed in various human cancers and the elevated Mcl-1 protein level has also been validated in cancer tissues, which underlines the importance of Mcl-1 for cancer cell survival." (PMID 36658493, 2023). "In two kinds of GC cells, the interference expression of OIP5-AS1/CD147/TRPM7 could induce the apoptosis of cancer cells by down-regulating the expression of BCL-2 and up-regulating the expression of Caspase3, Caspase9 and BAX." (PMID 38156103, 2023). "As a member of anti-apoptotic proteins, the role of Bcl-2 in cancer progression has been well illustrated, whereas the biological function of Claspin in tumorigenesis remains largely unknown." (PMID 38110764, 2023). "MOMP-dependent global mRNA decay may lead to preferential transcription of Bcl-2 and Bcl-xL mRNA, particularly under mild or transient stress conditions, to support cancer progression." (PMID 37612409, 2023). "Thus, the decreased Bcl-2/Bax ratio of cancer cells would be beneficial for reversing drug resistance in chemotherapy." (PMID 37497002, 2023). "Therefore, the regulation of the anti-apoptotic Bcl-2 protein has a critical function in treating carcinoma." (PMID 36677841, 2023). "Therefore, the Bcl-2 protein was identified as a possible therapeutic target for carcinoma treatment." (PMID 36677841, 2023). "It has been reported that the downstream of Akt protein, Bcl-2, is involved in the anti-apoptotic process of a variety of cancer cells, leading to a decrease in cytotoxicity and drug resistance, B7-H3 upregulates the expression of Bcl-2 and promotes drug resistance." (PMID 35684481, 2022). "Several Bcl-2 inhibitors have been extensively studied against various cancers." (PMID 36309485, 2022). "In addition to its role in apoptosis, recent work has demonstrated novel roles for Bcl-2 in modulating mitochondrial bio-energetics and in cancer metastasis and invasion." (PMID 36099249, 2022). "It was reported that sick persons with high expression of BCL-2 gene had relatively good pathophysiological behavior, which can be used as one of the molecular biological indicators to predict the development of lymph node metastasis in cancer patients." (PMID 36313628, 2022). "Finally, the expression level of the bcl2 gene is critical for the migration and invasion of cancer cells." (PMID 36233156, 2022). "Specifically, TSA upregulates bax and cleaved caspase 3 and downregulates BCL-2 in cancer cells." (PMID 36233012, 2022). "To further investigate the underlying mechanisms of anti-cancer activity of Ova, we briefly compared three important indicators from mRNA expressions in evaluating the possible inhibition activities on AGS, including caspase-3, Bcl-2 and Bax." (PMID 35163851, 2022). "The strong expression of Bcl-2 in the lamina propria was also additionally semi-quantitatively confirmed by immunofluorescence staining data, which detected a strong Bcl-2-positive cell population in all samples, with normal and low-grade cancer tissues displaying strong intensity." (PMID 36013602, 2022). "Therefore, it is of interest to document the molecular docking analysisdata of lupeol with different cancer targets such as Caspase- 3, BCL-2, Topoisomerase, PTK, mTOR, H-Ras, PI3K, and AKT." (PMID 36518133, 2022). "Bcl-2, a proto-oncogene, can inhibit cancer cell apoptosis, while Bax is a pro-apoptotic gene." (PMID 36465612, 2022). "Most of the currently available senotherapies for cancers are still restricted to Bcl-2 targeting." (PMID 35449130, 2022). "A major mechanism of action of artemisinin and its derivatives against cancer cells is the induction of apoptosis, which leads to activation of caspase-3 by elevating the expression of the Bax/BCl2 ratio and inducing the release of cytochrome c from mitochondria." (PMID 36359230, 2022).